HMGA1 (high mobility group AT-hook 1)
Diseases named in the same sentence as HMGA1 in open-access papers (continued):
Sharing a sentence is not in itself a finding about the gene and the disease.
cancer (continued). "Further analysis of cancer-related genes showed that TPA and mezerein exposure upregulates several oncogenes, including Hmga1, Foxm1, Igf2bp2, Anln, Ezh2, and Suz12." (PMID 40182023, 2025). "Rearrangement of TBL1XR1 (3q26.32) have been identified in various cancers involving different genes, including RARA (17q21), HMGA1 (6p21), TP63 (3q28), RET (10q11.2), and PIK3CA (3q26.32)." (PMID 41123735, 2025). "At the protein level, CPTAC dataset via UALCAN also confirmed HMGA1 overexpression in BRCA, COAD, OV, and other cancers (all p < 0.01)." (PMID 41463532, 2025). "We further found that HMGA1 depletion sensitizes ESCC to olaparib, suggesting a potential therapeutic target for enhancing cancer treatment efficacy." (PMID 39690136, 2024). "In age-related cancers such as lung cancer, breast cancer, colorectal cancer, and prostate cancer, elevated expression of HMGA1 and HMGA2 is correlated with increased self-renewal, invasiveness, and drug resistance in cancer cells." (PMID 39507236, 2024). "Moreover, cells with high and low HMGA1 also showed a polarised expression of pro-inflammatory genes, which were more likely to be expressed in the low HMGA1 cells, suggesting that HMGA1 may buffer the pro-inflammatory phenotype in human cancers." (PMID 39134516, 2024). "Using the TCGA dataset, HMGA1 expression was identified to have a positive correlation with FOXM1, especially in LUAD, LIHC and PAAD, suggesting their common importance in cancer." (PMID 37240870, 2023). "IGF2BP2 has the ability to stabilize HMGA1 mRNA and RAF196 mRNA, thereby enhancing cancer cell viability and promoting cancer cell proliferation." (PMID 37631029, 2023). "We further analyzed and compared the protein level of HMGA1 and FOXM1 in cancer tissues and normal ones based on the immunohistochemical staining." (PMID 37240870, 2023). "In prolactinomas and growing prolactinomas, PADI2 and PADI4 can promote the upregulation of the HMGA1, N-MYC and IGF-1 oncogenes by catalyzing the citrullination of histones, thus promoting the proliferation of cancer cells." (PMID 37020554, 2023). "To date, such molecular pathways are known that regulate the expression and activity of NAMPT in cancers, such as c-MYC/NAMPT/SIRT1, HMGA1/NAMPT/NAD+, FOXO1/NAMPT, NAMPT/miRNA, SIRT6/SIRT1/NAMPT, C/EBPβ/NAMPT." (PMID 37175631, 2023). "Our results provide a deep understanding of the biological function of HMGA1 and FOXM1 in cancer cell proliferation." (PMID 37240870, 2023). "By manipulating proliferative signals, HMGA1 and FOXM1 have become important molecules involved in cancer development and progression." (PMID 37240870, 2023). "The expression levels of HMGA1 mRNA and protein in HCC tissue and normal liver tissue were analyzed based on the cancer genome atlas, the gene expression omnibus and the Human Protein Atlas databases." (PMID 36705364, 2023). "Herein, we harnessed RNA sequencing technologies, cancer data analysis, analysis of public CRISPR data, pharmacological profiling and relevant experiments to uncover novel treatment strategies related to HMGA1 in iCCA." (PMID 36978140, 2023). "An increased protein level of HMGA1 and FOXM1 in LUAD and LIHC cancer tissues was detected compared to normal ones." (PMID 37240870, 2023). "Previous proteomic interactome studies have mainly utilized IP of HMGA1, followed by SDS-PAGE protein separation and MS analysis, in HEK293 and human cancer cells." (PMID 36835656, 2023). "To further determine their biological effects in cancers, we first collected all significantly changed genes in HMGA1- or FOXM1-overexpressed samples, and made the intersection within the three cancers LUAD, LIHC and PAAD." (PMID 37240870, 2023). "In this study, we found that high expression of HMGA1 and FOXM1 is a common molecular event in a variety of cancers, and they have common effects on cell cycle." (PMID 37240870, 2023).
cancer (continued). "Utilizing the TCGA database, mRNA expression levels of HMGA1 and FOXM1 were compared between various cancers and the corresponding normal tissues." (PMID 37240870, 2023). "Compared with the control group, the half-life time of HMGA1 mRNA was significantly reduced in cancer cells with depleted YB1 expression, indicating the important role of YB1 in regulating HMGA1 mRNA stability." (PMID 37035211, 2023). "Many studies have reported that c-Myc targets the promoters of HMGA1 and HMGA2, transcriptionally enhancing their expression in various types of cancer, including PDAC." (PMID 37370109, 2023). "Expression analysis detected HMGA1-high cancer cells (HMGA1 expression level>2), CD44-high cancer cells (CD44 expression level>2) and double-positive cancer cells in the integrated TNBC cohorts." (PMID 35611554, 2022). "The upregulation of mRNA expression of several oncogenes, including FOSL2, TUFT1, HMGA1, and HDGF, most often leads to the acquisition of cisplatin resistance, while increasing the proliferation of cancer cells and reducing their apoptosis." (PMID 36139487, 2022). "Indeed, several works demonstrated that HMGA1 expression is correlated with high tumour grade and metastasis formation, resistance to therapies and poor prognosis in a large set of human malignant neoplasias, and it is directly involved in the development and progression of cancer." (PMID 35504904, 2022). "This multiple-microtissue transcriptome analysis revealed three cancer cell-type clusters in the primary tumor and axillary lymph node metastasis, two of which were cancer stem cell (CSC)-like clusters (CD44/MYC-high, HMGA1-high)." (PMID 35611554, 2022). "Among the five genes, the mechanism of HMGA1, MPZL1, RACGAP1, and SNRPB in cancer progression were reported in several prior studies." (PMID 35205612, 2022). "Previously, accumulated evidence has demonstrated that HMGA1 is overexpressed and plays diverse tumor-promoting effects in HCC and other cancer types." (PMID 35785026, 2022). "Our findings provide new insights into the role of HMGA1 and MYH9 in gliomagenesis and suggest the potential application of HMGA1 and MYH9 in cancer therapy in the future." (PMID 34887392, 2021). "While intranuclear HMGA1 contributes to inflammation by modulating expression of cytokines, chemokines, and their receptors, the existence of extracellular-HMGA1 (eHMGA1) opens many avenues for further HMGA1 interactions that could drive both inflammation and cancer." (PMID 34572547, 2021). "Similar HMGA1 modifications were described for B16F10 and H1299 cancer cells induced into senescence by DNA damage." (PMID 34205514, 2021). "For instance, some years ago, down-regulation of a subset of miRNAs that target HMGA1 and HMGA2 (proteins overexpressed in malignant neoplasms) were identified in PitNETs." (PMID 32316225, 2020). "LIN28A and LIN28B regulate proliferation by directly or indirectly binding to and affecting the expression levels of cancer growth-related genes, including HER2 and HMGA1, in both let-7-dependent and -independent manners in breast cancer." (PMID 32967226, 2020). "The overexpression of these HMGA1 pseudogenes (HMGA1Ps) also increases the levels of HMGA2 and other cancer-related genes, such as EZH2 and VEGF, by inhibiting the suppression of their synthesis." (PMID 32341372, 2020). "Although HMGA1P6, HMGA1, and HMGA2 were all overexpressed in HGSOC, only HMGA1P6 and HMGA237 correlated with poor prognosis in cancer patients." (PMID 32127525, 2020). "In this sense, HMGA family members (HMGA1 and HMGA2) comprise an important group of genes involved in cancer genesis and progression." (PMID 31737655, 2019). "IGF2BP2 mediates stabilization of HMGA1 mRNA and production of IGF2 which synergistically drive cancer progression." (PMID 31852504, 2019).
cancer (continued). "We demonstrate that HMGA1 and FOXM1 regulate a common gene network, characterized by factors with a clear role in cancer EMT, migration, and angiogenesis, key processes involved in conferring aggressiveness to TNBC." (PMID 31311575, 2019). "Both miR‐4465 and miR‐26‐5p have been shown to suppress tumor proliferation and metastasis in several cancers by directly targeting EZH2 and HMGA1." (PMID 31402562, 2019). "In this sense, HMGA family members (HMGA1 and HMGA2) comprise an important group of genes involved in the genesis and progression of malignant tumors." (PMID 31737655, 2019). "Two HMGA1 (high mobility group AT-hook 1) pseudogenes, HMGA1P6 and HMGA1P7, were recently identified and shown to play critical roles in cancer progression as miRNA decoys for other genes." (PMID 29702599, 2018). "Increased activity of let-7 allows negative regulation of cancer factors such as RAS, MYC, HMGA1, and HMGA2; in other words, the origin and maintenance of CSCs are impeded." (PMID 29853899, 2018). "Together, these data demonstrate that an anti-correlation between HMGA1 expression and NOTCH1 activity is evident in cancer and that this correlation can be prognostic of patient outcome." (PMID 29743479, 2018). "We identified 15 highly connected hub genes in MEtan, including ABCA8, AFP, EGR3, EXO1, HMGA1, MT1X and VARS, which play roles as major regulators in cell-cycle regulation and cancer development." (PMID 27220887, 2016). "Neural lineage markers, such as NCAM1 (early) and NPTX1 (neuronal), were highly expressed in 143BNSC tumours, whereas genes involved in cancer proliferation, including EYA2, VCAN, HMGA1 and TXNIP, were highly expressed in 143BGBM tumours." (PMID 27551510, 2016). "However, no studies have evaluated HMGA1P1, HMGA1P2 and HMGA1P3 expression in human normal and malignant tissues where their possible deregulated expression might have consequences on the function of the wild type HMGA1 protein and then influence cancer progression." (PMID 26895108, 2016). "HMGA1 belongs to the family of non-histone chromatin-associated high-mobility group proteins involved in various cellular processes including heterochromatin organization, regulation of gene transcription, DNA replication and it is overexpressed in malignant neoplasms but not in normal adult cells." (PMID 25314274, 2014). "Subsequently, to define the role of the PI3-K/Akt pathway in the antineoplastic drug resistance of cancer cells overexpressing HMGA1, we silenced Akt with a shRNA in GEO CR and FRO cells overexpressing HMGA1." (PMID 25409711, 2014). "High Mobility Group A proteins (HMGA1 and HMGA2) are architectural nuclear factors involved in development, cell differentiation, and cancer formation and progression." (PMID 23936116, 2013). "Like HMGA1, COX-2 over-expression has also been demonstrated in many other cancers, including breast, colorectal, head and neck, esophageal and non-small-cell lung cancers, and prostatic hyperplasia." (PMID 22912571, 2012). "Although post-translational modifications such as acetylation and phosphorylation have been shown to modulate HMGA1’s activity, these regulatory layers have also not been systematically investigated across cancer types." (PMID 41463532, 2025). "Even though SOX12 was not related to miR‐296‐5p and HMGA1 was positively correlated with miR‐296‐5p, their interactions were reported in other cancers." (PMID 39995883, 2025). "HMGA1 chromatin regulators are also among the most abundant, non-histone chromatin binding proteins within the nuclei of cancer cells." (PMID 40076747, 2025). "qPCR was used to compare relative HMGA1 NAT levels between human epithelial and cancer cells." (PMID 41183073, 2025). "Additionally, we assessed BRCA1 and BRCA2 expression in normal esophageal cells and EC cells and found that HMGA1, BRCA1, and BRCA2 were highly expressed in cancer cells." (PMID 39690136, 2024).
cancer (continued). "HMGA1, as a highly conserved non-histone protein, can interact with multiple transcription factors to control the activation and transcription of cancer-related genes." (PMID 39591457, 2024). "Taken together, these findings reveal a mechanistic link between HMGA1 and PARP1 in regulating cell responses to DNA damage and suggest that targeting HMGA1 could be a promising strategy to increase cancer cell sensitivity to olaparib." (PMID 39690136, 2024). "Lacking YB1 protection enhanced HMGA1 mRNA degradation, which potentially induced cancer cell apoptosis and proliferation inhibition." (PMID 37035211, 2023). "To give a further demonstration, we collected cancers by setting the criteria that both HMGA1 and FOXM1 were no less than two-fold higher and the correlation coefficient was greater than or equal to 0.5." (PMID 37240870, 2023). "The high-mobility group A (HMGA1) protein participates in the regulation of NAMPT expression through NAD+-mediated enhancement of the NF-κB activity, contributing to the inflammatory environment and stimulating cancer progression." (PMID 37175631, 2023). "Furthermore, we explored the expression and effects of HMGA1 and FOXM1 in cancer, and their regulatory mechanism of cell cycle." (PMID 37240870, 2023). "Of note, several of these genes (such as Grem1, Hmga1, and Krt13) are specifically expressed by cancer cells, but not by other cell populations, indicating that these genes are potential markers associated with tumor metastasis." (PMID 37190324, 2023). "Thus, our results provide the basic evidence that HMGA1 and FOXM1 cooperatively accelerate cell cycle progression by up-regulating PLK1 and CCNB1 to promote cancer cell proliferation." (PMID 37240870, 2023). "The expression levels of EP400, HMGB2, CDK1, PPARG, and MVK were found to be significantly correlated with HMGA1 expression level in both analyzed cancer subtypes but not in non-cancerous tissue of the lung." (PMID 35805937, 2022). "The expression of the HMGA1, coding non-histone transcription regulator HMGA1, was previously proved to correlate with the ability of cancer cells to metastasize the advancement of the disease." (PMID 35948739, 2022). "First, the differential expression of the HMGA1 between various cancers and noncancerous tissues from healthy individuals was assessed via the Oncomine platform." (PMID 35805937, 2022). "HMGA1 promotes ATM expression and enhances cancer cell resistance to genotoxic agents." (PMID 34716319, 2021). "Thus, in addition to the RSPO3 proteins, HMGA1 and TFAP4 activate the WNT/β-catenin pathway, stimulate cell migration and invasion and promote cancer progression." (PMID 34021172, 2021). "If secreted HMGA1 is a common feature in settings beyond TNBC cells, this could have important implications in cancer biology." (PMID 34572547, 2021). "Furthermore, the up-regulation of matrix metalloproteinase-2 (MMP-2) by HMGA1 promotes lung cancer transformation, and the blocking of MMP-2 expression inhibits cancer cell migration and invasion." (PMID 34072941, 2021). "The HMGA1 protein is an architectural chromatin protein that is abundantly expressed during embryonic development and in most cancer tissues, but is weakly expressed or absent in normal adult tissues." (PMID 33194665, 2020). "HMGA1 has also been demonstrated to activate phosphoinositide 3-kinase (PI3K)/AKT and mammalian target of rapamycin complex 1 (mTORC1) pathway, which strongly inhibits autophagy in cancer cells." (PMID 32477928, 2020). "HMGA1 is a well-known architectural factor that frequently elevates in rapidly proliferative cells (such as embryonic stem cells) and diverse cancer cells, with absent or low levels in normal, differentiated, adult tissues." (PMID 33536877, 2020). "Interestingly, HMGA1 is a direct target of miRNAs regulating EMT and migration in different cancer types." (PMID 31963852, 2020).
cancer (continued). "Given the potential role of FOXM1 as a molecular partner of HMGA1, we searched for a relationship between HMGA1 and FOXM1 in The Cancer Genome Atlas (TCGA), a public database collecting information from a high number of cancer patients obtained from high-throughput approaches." (PMID 31311575, 2019). "Since the target genes analyzed are key factors of several cancer hallmarks such as EMT, migration and angiogenesis, we next considered the possibility that HMGA1 and FOXM1 could act in concert in mediating cancer-related cell abilities." (PMID 31311575, 2019). "It has been reported that two recently identified HMGA1-pseudogenes, HMGA1P6 and HMGA1P7, may play a role in PitNETs development protecting, by a ceRNA-sponge mechanism, HMGA1, HMGA2, and other cancer-related gene mRNAs from miRNAs able to target their 3′UTR." (PMID 31487906, 2019). "Indeed, silencing of CCAT1 led to downregulation of many genes involved in cancer cell proliferation, survival and metastasis, such as EGFR, CDK4, YES1, PAK4, and HMGA1." (PMID 30190462, 2018). "These cells, likely CSCs, express high levels of both HMGA1 and HMGA2; this might constitute an essential element of resistant cancer cells characterized by well-defined self-renewal and invasion factors." (PMID 29853899, 2018). "Knockdown of Hmga1 in a PDAC cancer cell line generated from a KP172CT;Hmga2CK/CK mouse had no impact on metastatic ability after intravenous transplantation." (PMID 30228296, 2018). "We also found a significant negative correlation between HMGA1 and HEY1 in various cancer types, which were not completely overlapping with those where HMGA1 and HEYL anti-correlate." (PMID 29743479, 2018). "Our investigation revealed the downstream events of phosphorylation that affect cancer cell proliferation, such as MCM2 promoting cell proliferation might possibly via the regulation of HMGA1 phosphorylation." (PMID 29038488, 2017). "Levels of HMGA1, HMGA2, PLAGL2, IGF2BP2, E2F5, and ARID3A transcripts were also inversely proportional to levels of Let-7 miRNA by examination of a cohort of 199 CRC patients from the TCGA Pan-Cancer analysis project." (PMID 26244988, 2015). "HMGA1 and HMGA2 may have a role in NSCLC cancer progression also by regulating the expression of miRNAs." (PMID 25859543, 2015). "Overexpression of HMGA1 and HMGA2 is a general feature of experimental and human malignancies and their overexpression is often correlated with aggressiveness, resistance to conventional anti-cancer therapies and poor prognosis." (PMID 25409711, 2014). "High-mobility group A1 (HMGA1) proteins are architectural chromatinic proteins, abundantly expressed during embryogenesis and in most cancer tissues, but expressed at low levels or absent in normal adult tissues." (PMID 24833610, 2014). "Interestingly, when CTSCs were stained for the cancer stem cell marker CD133 and then sorted, HMGA1 expression was enriched in CD133+ cells." (PMID 24833610, 2014). "In fact, HMGA1 proteins are the most abundant nonhistone chromatin binding proteins found in cancer cells." (PMID 23658826, 2013). "Based on the observation that HMGA1 sequestration resulted in reduced HMGA1 protein levels, we consider the possibility that an autoregulatory negative feedback mechanism may be involved in regulating HMGA1 levels in cancer cells." (PMID 41183073, 2025). "However, the relationship between HMGA1 and responses to mTOR inhibitors in cancer has not been reported." (PMID 38725843, 2024). "Furthermore, HMGA1 facilitates EMT and tumor metastasis in cancer." (PMID 39610830, 2024). "Indeed, HMGA1 is among the most abundant, nonhistone chromatin-binding proteins within nuclei of cancer cells where it induces genes expressed in stem cells and tumor progression." (PMID 36919699, 2023). "Similarly, in our study, the level of HMGA1 expression measured in cancer tissue was not connected with age, gender, or smoking status." (PMID 35948739, 2022).